FBXO7 (F-box protein 7)
Description:
Substrate recognition component of a SCF (SKP1-CUL1-F-box protein) E3 ubiquitin-protein ligase complex which mediates the ubiquitination and subsequent proteasomal degradation of target proteins and plays a role in several biological processes such as cell cycle, cell proliferation, or maintenance of chromosome stability. Recognizes and ubiquitinates BIRC2 and the cell cycle regulator DLGAP5. Plays a role downstream of PINK1 in the clearance of damaged mitochondria via selective autophagy (mitophagy) by targeting PRKN to dysfunctional depolarized mitochondria. Promotes MFN1 ubiquitination. Mediates the ubiquitination and proteasomal degradation of UXT isoform 2, thereby impairing the NF-kappa-B signaling pathway. Inhibits NF-kappa-B pathway also by promoting the ubiquitination of TRAF2. Affects the assembly state and activity of the proteasome in the cells including neurons by ubiquitinating the proteasomal subunit PSMA2 via 'Lys-63'-linked polyubiquitin chains (By similarity). Promotes 'Lys-48'-linked polyubiquitination SIRT7, leading to the hydrogen peroxide-induced cell death.
Synonyms: FBX7; Fbx; PARK15; FBX07; PKPS
Tractability: PROTAC: ubiquitination databases record sites on it; its protein half-life has been measured.
Gene: Protein-coding gene on chromosome 22 (32,474,676 to 32,498,831, forward strand). Ensembl gene ENSG00000100225.
Subcellular location: Cytoplasm; Nucleus; Mitochondrion; Cytoplasm, cytosol
Subcellular location (Human Protein Atlas): Cytosol; Nucleoplasm
Pathways (Reactome):
Immune System: Antigen processing: Ubiquitination & Proteasome degradation
Metabolism of proteins: Neddylation
Gene Ontology:
Molecular function: protein binding; protein heterodimerization activity; protein kinase binding; ubiquitin binding; ubiquitin protein ligase binding; ubiquitin-like ligase-substrate adaptor activity; ubiquitin-protein transferase activity
Biological process: autophagy of mitochondrion; negative regulation of canonical NF-kappaB signal transduction; negative regulation of oxidative stress-induced neuron intrinsic apoptotic signaling pathway; positive regulation of mitophagy; proteasome-mediated ubiquitin-dependent protein catabolic process; protein K48-linked ubiquitination; protein localization to mitochondrion; protein ubiquitination; regulation of locomotion; regulation of neuron projection development; regulation of protein stability; SCF-dependent proteasomal ubiquitin-dependent protein catabolic process; ubiquitin-dependent protein catabolic process; positive regulation of autophagy of mitochondrion
Cellular component: classical Lewy body; cytoplasm; cytosol; glial cytoplasmic inclusion; Lewy body core; Lewy body corona; Lewy neurite; mitochondrion; nucleoplasm; nucleus; protein-containing complex; SCF ubiquitin ligase complex; ubiquitin ligase complex
Genetic constraint (gnomAD): Loss-of-function variants: 28 observed, 40.18 expected, observed/expected ratio (o/e) 0.7, 90% interval 0.51 to 0.95. The upper end of that interval is the gene's LOEUF score, 0.95, which puts it in group 4 of 6, group 1 being the genes least tolerant of losing a copy. Missense variants: 607 observed, 606.41 expected, observed/expected ratio (o/e) 1, 90% interval 0.94 to 1.07. Synonymous variants: 238 observed, 238 expected, observed/expected ratio (o/e) 1, 90% interval 0.9 to 1.11.
Homologues: Orthologues: chimpanzee FBXO7 (99% identical), macaque FBXO7 (95% identical), pig FBXO7 (85% identical), rabbit FBXO7 (83% identical), dog FBXO7 (81% identical), guinea pig FBXO7 (74% identical), mouse Fbxo7 (73% identical), rat Fbxo7 (73% identical), tropical clawed frog fbxo7 (49% identical), zebrafish fbxo7 (37% identical).
Diseases named in the same sentence as FBXO7 in open-access papers:
FBXO7 is named in the same sentence as 53 diseases in open-access papers, as found by Europe PMC text mining. Sharing a sentence is not in itself a finding about the gene and the disease. The quoted sentences say what the papers report.
Parkinson disease (48 papers, 2011 to 2026). A progressive degenerative disorder of the central nervous system characterized by loss of dopamine producing neurons in the substantia nigra and the presence of Lewy bodies in the substantia nigra and locus coeruleus. "A second link between Skp1 and neuronal function was lately provided by the identification of parkinsonism-causing mutations in PARK15/FBXO7, a Skp1-interacting protein." (PMID 37644186, 2024). "The E3 ligase FBXO7 has both ubiquitin-dependent and independent functions and is closely associated with Parkinson’s disease and cancer." (PMID 38839752, 2024). "FBXO7 (F-box-only protein 7) gene mutations have been identified in a number of families with severe autosomal recessive early-onset Parkinson’s disease." (PMID 37892117, 2023). "At the same time, recessive variants (ATP13A2, PLA2G6, and FBXO7) show earlier onset age and represent pure Parkinsonism along with additional clinical features." (PMID 36909056, 2023). "Fbxo7 misregulation and mutation are associated with a variety of pathological conditions, from anemia, male sterility, cancer, and Parkinson’s disease, demonstrating its critical role in multiple cell types." (PMID 35670764, 2022). "Of those, five patients presented MDs such as dystonia or parkinsonism, spasticity, and suspicion of brain iron deposits or GP hypointensities; they were associated with variants in FBXO7, FUCA1, GLB1, TPP1, and KIF1A." (PMID 36233161, 2022). "Fbxo7 (F-box protein only 7) is a clinically important protein implicated in a variety of pathologies, including anemia, cancer, and Parkinson’s disease." (PMID 35670764, 2022). "Mutations in FBXO7/PARK15 are associated with both sporadic Parkinson's disease and a severe form of autosomal recessive early‐onset Parkinsonism." (PMID 31144295, 2019). "In 2008, a point mutation in FBXO7 was linked to a familial form of PD 5, presenting an early‐onset Parkinsonism with pyramidal signs." (PMID 31144295, 2019). "Parkinson’s disease-linked FBXO7 can recruit parkin into damaged mitochondria and facilitate its aggregation." (PMID 28273839, 2017). "Subsequently, also named PARK15, Fbxo7 was found to interact directly with two other genes mutated in Parkinson’s disease, PINK1/PARK6, and Parkin/PARK2, to promote mitophagy." (PMID 27915416, 2017). "Fbxo7 is a clinically relevant F-box protein, associated with both cancer and Parkinson's disease (PD)." (PMID 27503909, 2016). "Mutations in the F-box only protein 7 (FBXO7) gene cause parkinsonian pyramidal disease (PPD- or PARK15-associated parkinsonism), an autosomal recessive neurodegenerative disease with juvenile onset, severe levodopa-response, and additional pyramidal signs." (PMID 25980689, 2015). "Recently, the F-box only protein 7 (FBXO7) mutations have been identified in several families with early-onset parkinsonism and pyramidal tract signs." (PMID 25029497, 2014). "Mutations in the FBXO7 gene have been identified to cause Parkinsonian-pyramidal syndrome, an autosomal recessive Parkinsonism with pyramidal tract signs." (PMID 24063688, 2013). "Mutations in the F-box protein 7 gene (FBXO7) have been identified to cause Parkinsonian-pyramidal syndrome, an autosomal recessive form of Parkinsonism." (PMID 24063688, 2013). "Recessive mutations in the F-box only protein 7 gene (FBXO7) cause PARK15, a Mendelian form of early-onset, levodopa-responsive parkinsonism with severe loss of nigrostriatal dopaminergic neurons." (PMID 23133663, 2012). "Multiple familial Parkinson’s disease–related gene studies conducted on several populations have identified mutations in F-box domain-containing protein (Fbxo7), which is the substrate recognition component of the Skp1-Cullin-F-box protein E3 ubiquitin ligase complex." (PMID 36260224, 2023). "A polymorphism of Park15 was found to be a protective factor against Parkinson's disease and so targeting FBXO7 may also be relevant for therapeutics." (PMID 34335440, 2021).
Parkinson disease (continued). "In addition to GWAS studies of the blood, similar studies on families with pedigrees showing cases of the early onset Parkinson’s disease revealed the homozygous inheritance of point mutations in FBXO7 to be causative." (PMID 27915416, 2017). "Therefore, in view of the importance of the F-box domain in the interaction with DAT, we studied the possible association of the transporter with other F-box proteins that have been implicated in Parkinson disease (such as FBXO7 or FBXO18) or in the stability of FBXL2 (such as FBXO3)." (PMID 34709416, 2021). "Collectively, these data support a model whereby the loss of FBXO7 expression in dopaminergic neurons affects a number of pathways which lead to cell loss in the SNpc, and a locomotor defect – two hallmark features of Parkinson's disease – from 20 weeks of age." (PMID 31144295, 2019). "Herein, it is revealed that FBXO7, a substrate‐recognition component of the SCF complex implicated in the pathogenesis of Parkinson's disease, confers mesenchymal properties and chemoresistance in GBM by controlling Rbfox2‐mediated alternative splicing." (PMID 37822160, 2023). "Reports suggest that mutations in ATP13A2, F-Box Protein 7 (FBXO7), and Phospholipase A2 Group (PLA2G) cause early-onset L-dopa-responsive Parkinsonism with pyramidal signs." (PMID 33532138, 2021). "Discovering new substrates of E3 ubiquitin-ligase SCF(Fbxo7) contributes to understand its function in different diseases such as cancer and Parkinson." (PMID 33010352, 2021). "Intriguingly, given Fbxo7’s role in Parkinson’s disease, a site for nuclear respiratory factor 1 (NRF1) was also found in its promoter." (PMID 33774278, 2021). "The F-box-protein 7 (FBXO7) mutations were found in typical and young onset Parkinson's disease, which plays an important role in the development of dopaminergic neurons." (PMID 31057651, 2019). "FBXO7/PARK15 is implicated in many human diseases, including cancers and early-onset Parkinson's disease." (PMID 26095538, 2015). "We also highlight recent advances in our understanding of Fbxo7 function in Parkinson's disease, where it functions in the regulation of mitophagy with PINK1 and Parkin." (PMID 24107298, 2013). "Mutations in the F-box only protein 7 gene (FBXO7) cause PARK15, an autosomal recessive neurodegenerative disease presenting with severe levodopa-responsive parkinsonism and pyramidal disturbances." (PMID 21347293, 2011). "Fbxo7 interacts with proteins involved in Parkinson’s disease, such as PARKIN15." (PMID 39568047, 2024). "Although mutation of FBXO7, which has been shown to destabilize FBXO7, is frequent in the neurons of Parkinson's disease, it's rare in GBM (data not shown)." (PMID 37822160, 2023). "Recently, mutations of F-box only protein 7 (FBXO7), an adaptor protein in Skp-Cullin-F-box ubiquitin E3 ligase complex (SCF complex), were found to induce early-onset juvenile autosomal recessive PD with rapidly progressive and serious PD symptoms (Parkinson disease-15, PARK15)." (PMID 33918863, 2021). "FBXO7 deficiency is a rare genetic condition described in 26 patients from 10 unrelated families, giving three major phenotypes: autosomal recessive juvenile‐onset levodopa responsive PPS (14 patients), SPG (7 patients), and isolated parkinsonism (5 patients)." (PMID 32767480, 2020). "Recently, we characterized mutations in the F-box only protein 7 (FBXO7) gene, encoding the F-box protein 7 (FBXO7), as the cause of PARK15, an autosomal recessive neurodegenerative disease presenting with juvenile, severe levodopa-responsive parkinsonism and additional pyramidal signs." (PMID 21347293, 2011). "Moreover, atypical or complex parkinsonism may be due to mutations in genes such as ATP13A2, DCTN1, DNAJC6, FBXO7, PLA2G6, and SYNJ1." (PMID 35328025, 2022). "Increased stability and overexpression of FBXO7 may be beneficial to Parkinson's disease." (PMID 31057651, 2019).
Parkinson disease (continued). "Mutations in the F-box protein 7 gene (FBXO7), encoding a protein of the F-box protein family, have been identified as a cause for Parkinsonian-pyramidal syndrome, an autosomal recessive neurodegenerative disease with severe levodopa-responsive Parkinsonism, and additional pyramidal signs." (PMID 24063688, 2013). "FBXO7/PARK15 was found mislocalized together with α-syn in Lewy bodies, Lewy neurites and cytoplasmic inclusions in glial cells in both Parkinson’s disease and MSA cases; Lewy body formation triggers the alterations in the expression level." (PMID 34019093, 2021). "FBXO7 gene regulates ubiquitin-dependent CyclinD/CDK6 degradation and maintains mesenchymal gene expression and mutations have been associated with Parkinson's disease but it's role in the liver has not been determined." (PMID 38291075, 2024). "At the moment, FBXO7 has been related to Parkinson’s disease, although to the best of our knowledge, it has not been directly involved in stroke." (PMID 35008673, 2021). "Nevertheless, UCHL1 and FBXO7 interact with ParkinIP proteins, and therefore the RelatedPD subnetwork consists of a single connected component when ATP13A2, which is responsible for Kufor-Rakeb syndrome, a form of parkinsonism with dementia and juvenile disease onset, is excluded." (PMID 24244333, 2013). "Other genes such as APT13A2, PLA2G6, FBXO7, and the more recently identified DNAJC6, SYNJ1, and VPSC13 are usually related to younger onset Parkinsonism, complicated by atypical motor and non-motor phenotypes." (PMID 34630269, 2021).
Parkinsonism (22 papers, 2011 to 2026). Characteristic neurologic anomaly resulting from degeneration of dopamine-generating cells in the substantia nigra, a region of the midbrain, characterized clinically by shaking, rigidity, slowness of movement and difficulty with walking and gait. "Autosomal recessive mutations in the FBXO7 (PARK15) gene are involved in a juvenile form of Parkinsonism with heterogenic phenotypes characterized by either a classic Parkinson’s disease (PD) phenotype, pyramidal tract signs only, or by a combination of Parkinsonism and pyramidal signs." (PMID 35701754, 2022). "We identified heterozygous variants in genes associated with recessive PD and parkinsonism, including one in DNAJC6, six in VPS13C, two in SYNJ1, three in PLA2G6 and one in FBXO7 in early-onset cases." (PMID 39867380, 2025). "Although no pathogenetic mutations in the FBXO7 gene were detected in 135 Chinese early-onset parkinsonism patients, the PD patients showed a trend toward decrease in Y52C G allele frequency compared with the controls." (PMID 25029497, 2014). "In particular, we envisage that more detailed investigations on experimental models of GBA1-, SYNJ1-, SYPH1-, TMEM230-, Parkin-, PINK1-, ATP13A2-, FBXO7- and SYT11-associated parkinsonism could provide new insight into the pathophysiological mechanisms leading to PD that may involve Rab dysfunction." (PMID 36009486, 2022).
parkinsonian-pyramidal syndrome (9 papers, 2009 to 2025). A Parkinson's disease that has material basis in mutation in the FBXO7 gene on chromosome 22q12.3. "Homozygous or compound heterozygous mutations in the F-box only protein 7 (FBXO7) gene located on chromosome 22q12.3 are associated with Parkinsonian-pyramidal syndrome (PPS) and AR EOPD (PARK15, OMIM 260300)." (PMID 34356877, 2021). "Mutation of FBXO7 is responsible for an early onset Parkinsonian pyramidal syndrome and genome-wide association studies have linked variants in FBXO7 to erythroid traits." (PMID 30840666, 2019). "Mutations within the FBXO7 (F-box only protein 7) gene have been shown to promote either a typical PD phenotype or an early onset form of parkinsonian-pyramidal syndrome." (PMID 29204154, 2017). "Mutations in another E3 ubiquitin ligase, F-Box Only Protein 7 (FBXO7), were identified as the cause of parkinsonian pyramidal syndrome, a rare form of ARJP which presents with pyramidal tract dysfunction." (PMID 31783880, 2019). "FBXO7 (PARK15) mutations are known to cause autosomal recessive juvenile- and early-onset PD with atypical pyramidal symptoms (Parkinsonian-pyramidal syndrome); the median age of onset of the phenotype associated with FBXO7 mutations is 17 years, but it can actually range from 10 to 52 years." (PMID 40362688, 2025).
neuroblastoma (5 papers, 2011 to 2023). Neuroblastoma (NB) is the most common solid, extracranial childhood tumor. "An alternate possibility is that Fbxo7 has recently been shown to bind and activate a degradative caspase pathway in neuroblastoma and HEK293T cells." (PMID 35670764, 2022). "Immunohistochemical analysis of human neuroblastoma SH-SY5Y cells revealed that endogenous FBXO7 and FOXO4 colocalized in cells." (PMID 34800438, 2021). "The localization pattern of WT- and mutant FBXO7 proteins in human neuroblastoma SH-SY5Y cells and mouse primary hippocampal neurons were similar to those described in HEK 293T cells." (PMID 21347293, 2011). "Small-molecule inhibitors of FBXO7 that interfere with the FBXO7–PINK1 interaction reduce mitochondrial injury and inflammation, leading to neuroprotection in primary cortical neurons, human neuroblastoma cells, and PD patient–derived cells." (PMID 36646384, 2023). "In addition, the interaction between endogenous FBXO7 and USP7 was confirmed in HEK293 and human neuroblastoma SH-SY5Y cells." (PMID 37874827, 2023). "In addition, the interaction between endogenous FBXO7 and endogenous FOXO4 was confirmed in HEK293 cells, mouse neuroblastoma MN9D cells, and whole mouse brain lysates." (PMID 34800438, 2021).
anaemia (4 papers, 2015 to 2025). "Fbxo7 hypomorphs showed regenerative anaemia associated with a shorter erythrocyte half-life, and male mice were infertile." (PMID 30840666, 2019). "In considering other causes for the anaemia in Fbxo7LacZ/LacZ mice, we reasoned that Fbxo7 also participates in mitophagy, and defects in mitophagy can lead to retention of mitochondria in RBCs, leading to their premature death due to accumulated ROS." (PMID 26095538, 2015). "This cell cycle regulatory role of Fbxo7 is important in erythropoiesis, and we have reported that the reduction of Fbxo7 in a mouse causes anaemia, caused by a failure of differentiating erythroblasts to withdraw from the cell cycle due to insufficient levels of p27." (PMID 27915416, 2017). "Our study eliminates transcriptional effects on p27, GATA1 or NF-E2 as underlying causes for anaemia but as Fbxo7 is a multi-functional E3 ubiquitin ligase, we cannot eliminate the possibility that it may also act via p27-independent mechanisms." (PMID 26095538, 2015). "Further, an Fbxo7-knockout mouse model exhibited impaired erythropoiesis and anemia with increased mean cell hemoglobin concentration." (PMID 39919746, 2025). "Here we show that Fbxo7 stabilizes p27 levels to ensure cell cycle arrest and that reduced Fbxo7 expression results in anaemia." (PMID 26095538, 2015). "We propose that the ∼90% reduction in Fbxo7 in mutant mice is a more severe phenotype, causing anaemia, than inheritance of rs11107 SNP, which does not." (PMID 26095538, 2015). "In contrast, the increased activated T cells could be linked to the shorter erythrocyte half-life and regenerative anaemia as it is only present in the whole body Fbxo7tm1a mice which would suggest it is triggered by the environment rather than an intrinsic role for FBXO7 within T cells." (PMID 30840666, 2019).
dementia (4 papers, 2013 to 2021). Loss of intellectual abilities interfering with an individual's social and occupational functions. "Among these, mutations in F-box only protein 7 (FBXO7) cause autosomal-recessive early-onset Parkinsonism with atypical features, including dementia, dystonia, hyperreflexia, and pyramidal signs." (PMID 34800438, 2021). "However recessive gene mutations of FBXO7 (PARK15) are associated with juvenile onset Parkinsonism frequently accompanied with atypical features including dementia, dystonia, hyperreflexia and pyramidal signs." (PMID 27090516, 2016).